MEG3 (maternally expressed 3)
Diseases named in the same sentence as MEG3 in open-access papers (continued):
Sharing a sentence is not in itself a finding about the gene and the disease.
cancer (continued). "Of the roughly 60+ lincRNAs that have been shown to be associated with various cancer types, majority of them are up-regulated in cancer and only a few lincRNAs are shown to be down-regulated in cancer samples including GAS5 and MEG3." (PMID 25933431, 2015). "A variety of lncRNAs, including ANRIL, MEG3 and HULC, either promote or suppress the development of cancer." (PMID 26448942, 2015). "Recent studies conducted in a plethora of cancers showed the success of CRISPR-Cas9 technology to effectively knock out the expression of HOTAIR, NEAT1, XIST, TUG1, and UCA1 and to effectively upregulate the expression of MEG3." (PMID 40282449, 2025). "The MEG3/miR-34a axis regulates NF-κB deacetylation through SIRT1, and this regulation has a significant impact on the inflammation and apoptosis of retina epithelial cells and on cancer biology in general." (PMID 40149464, 2025). "Some lncRNAs (such as PTENP1, MEG3, and ZNF667-AS1) were downregulated in cancer samples." (PMID 40265013, 2025). "The high clonogenic activity of HAN-1 cells can be related to increased expression of several long non-coding RNAs, such as TUG1, MEG3, MALAT1, NEAT1, and DANCR – all considered as modulators of stemness of cancer cells, their differentiation potential and chemoresistance." (PMID 38342891, 2024). "Another lncRNA, MEG3, has been explored in the context of UPR in various cancers." (PMID 39448589, 2024). "MEG3 inhibits EC progression, while PSMG3-AS1 promotes the invasion of this cancer." (PMID 38893244, 2024). "Promoter methylation of MEG3 and GAS5 is one of the mechanisms of down-regulation in cancers." (PMID 37568568, 2023). "LncRNAs have been shown to be expressed in all major cancer types, contribute to the hallmarks of cancer, and can act as oncogenes (“onco-lncRNAs”, such as HOTAIR, NEAT1 and MALAT1) or tumor suppressors (e.g. GAS5, MEG3, NBAT and LINC-PINT)." (PMID 37346034, 2023). "During the past years, MEG3 and HOTAIR expression has been investigated in various cancer types; however, the precise molecular mechanism by which these lncRNAs promote tumorigenesis remains unclear." (PMID 35186192, 2022). "MEG3 physically interacts with the EZH2 subunit of the PRC2 complex to repress the expression of several genes involved in TFG-β signaling (e.g., SMAD2 or TGFBR1), increasing the aggressiveness of cancer by promoting invasion and metastasis." (PMID 35054945, 2022). "MEG3 promotes EZH2 ubiquitination, leading to upregulation of LATS2, a tumor suppressor kinase that inhibits cell proliferation and metastasis through the Hippo signaling pathway in several types of cancer." (PMID 35054945, 2022). "The first evidences of the contribution of MEG3 in human cancers were obtained from pituitary non-functioning adenomas." (PMID 34220951, 2021). "In addition to the validation of commonly studied protein gene targets, we also identified two specific LincRNAs, MEG3 and LINC01133, which specifically represented one of the cancer cell clusters respectively." (PMID 34055623, 2021). "Although there is a lack of clear evidence demonstrating the effect of MEG3 on cancer stemness, several studies have revealed that modulation of MEG3 affects the expression of EMT transcription factors and mesenchymal properties." (PMID 34069546, 2021). "Our results demonstrate that MEG3 may be a useful prognostic marker for HGSOC patients, and its inactivation participates in the regulation of cancer cell development and progression." (PMID 32295169, 2020). "The most prolific lncRNAs, with ≥16 recorded cancer types, are HOTAIR, MALAT1, MEG3 and H19." (PMID 32024996, 2020). "For example, the lncRNA MEG3 shared multiple PCGs with six other lncRNAs, of which three (TP73‐AS1, LINC00472 and LINC00473) were also confirmed to be of biological significance in cancer." (PMID 32460441, 2020). "Earlier studies reported that MEG3 expression was abnormally low or even absent in various cancer tissues and cancer cell lines." (PMID 32277605, 2020).
cancer (continued). "MEG3 was reported to positively regulate EMT in lung and ovarian cancer." (PMID 32612992, 2020). "The stage-specific network analysis led to the prediction of an important module, entitled the MEG3 module, containing some key cancer-related coding and non-coding genes." (PMID 31182759, 2019). "In several previous reports on other cancer types, either MEG3 or DLK1 was reported to become deregulated, but not both." (PMID 29348851, 2017). "These cancers also shared three seed genes (H19, MALAT1 and MEG3)." (PMID 28051121, 2017). "A likely lncRNAs profile will include, among others, HOTAIR, MEG3, NEAT1, UCA1, and/or AK126698 in cancer-drugs cisplatinum-based therapies, and the recently proposed GAS5, UCA1, BC087858 and SOX2-OT involved in the gene-target therapies as EGFR-TKIs based oncological treatments." (PMID 28904641, 2017). "However, some have been reported playing critical roles in cancer, such as H19, GUCY1B2, MEG3 and AKR7L." (PMID 25928635, 2015). "Other lncRNAs involved in various types of cancers include HOTAIR, MEG3, PVT1 and CDKN2B-AS1." (PMID 26305674, 2015). "Another example is the lncRNA, MEG3, which is highly expressed in non-neoplastic tissues, but lowly expressed in cancer tissues." (PMID 26485761, 2015). "Human MEG3 is an approximately 1.7 kb lncRNA that is expressed at high levels in brain tissues but at very low levels or is absent in cancer tissues and cell lines." (PMID 25428918, 2014). "We found that two lncRNAs - MEG3 (Maternally Expressed Gene 3) and KIAA0125 - compete for the role of the first hub and regulate the expression of the almost totality of the mRNAs in the cancer-MMI-network, by antagonizing mir-379 and mir-150, respectively." (PMID 25033876, 2014). "To investigate whether MEG3 had a direct functional role in facilitating cell invasion in NSCLC, we evaluated cancer cell invasion through transwell matrigel assay." (PMID 24098911, 2013). "MEG3 expression was not detectable in various brain cancers, nor in a range of human cancer cell lines implicating a potential role of this lncRNA in suppression of cell growth." (PMID 21489289, 2011). "Although previous studies provided insights into how MEG3 might function in the progression of cancer, most of them failed to explore that RNA-protein interactions were fundamental for RNA to function." (PMID 40548301, 2025). "Interestingly, our study also revealed hub genes (MEG3, MIAT, IRF1, ADAMTS9-AS2, TP63, NOD2, NOD1, NLRP3, MAGI2-AS3, and PVT1, respectively) within the pyroptosis-related ceRNA network, some of which have been well-studied in the field of cancer biology." (PMID 37511974, 2023). "And, strictly speaking, as knockdown of MEG3 only partly abolished the activation of DDP-induced NLRP3/caspase-1/GSDMD pathway and anti-cancer functions in MDA-MB-231 cells, MEG3 may partially mediated the pyroptotic signaling upon DDP treatment in this type of TNBC cell line." (PMID 34326697, 2021). "Collectively, these studies imply that downregulation of MEG3 in cancer cells may convert the non-CSCs into a CSC phenotype." (PMID 34069546, 2021). "However, our study does not determine if the high MEG3 expression represents increased stromal infiltration in the tumors or elevated expression in cancer cells." (PMID 32612992, 2020). "According to lnc2Cancer, the most studied cancer-associated lncRNAs are MALAT1, H19, HOX antisense intergenic RNA (HOTAIR), maternally expressed 3 (MEG3), taurine upregulated 1 (TUG1), antisense non-coding RNA in the INK4 locus (ANRIL) and nuclear-enriched abundant transcript 1 (NEAT1)." (PMID 32340118, 2020).
cancer (continued). "In conclusion, we characterized DE miRNAs and lncRNAs between HCC and adjacent non-cancer tissues and constructed a MLMI network based on validated reciprocal interactions between ncRNAs and mRNAs in HCC, as well as identified a novel isoform of MEG3 for the first time." (PMID 31695090, 2019). "As emerging stars in cancer biomarkers, more and more lncRNAs were identified, and some functioned as oncogenes, such as CCAT2, HOTTIP and TUG1, while some may be acted as tumor suppressor genes, such as MEG3, GAS5, ANRIL." (PMID 28977885, 2017). "Our results also suggested that imprinting defects at MEG3-DMR (DMR-3) were not a significant contributor to cancer development but could potentially hasten the disease process." (PMID 26802029, 2016). "Additionally, because MEG3 and RTN1C can induce apoptosis in cancer cells, determining whether RTN1C is regulated by MEG3 in cancer models may be worth further investigation." (PMID 25559585, 2015). "Indeed, an overlay of nucleosome prediction at all analyzed regulatory regions (DLK1 promoter, MEG3 and IG DMR) with our experimentally obtained methylation patterns suggest strongly positioned and potentially newly phased nucleosomes in cancer compared to benign urothelial cells." (PMID 25741387, 2014). "In particular, altered nucleosomal positioning could account for the peculiar patterning of DNA methylation at the MEG3 DMR, where one specific CpG site (#6) became significantly hypomethylated in cancer cells, while methylation of flanking sites rather increased." (PMID 25741387, 2014). "Unlike MEG3, 7SL lncRNA is highly expressed in cancer cells." (PMID 25543668, 2014). "However, many lncRNAs have been found to be differentially expressed in a variety of cancers and may act as either oncogenes, such as MALAT-1, HOTAIR, and ANRIL, or tumor suppressor genes, such as MEG3, lincRNA-p21, and PTENP1, in cancer development." (PMID 24036441, 2013). "To characterize the specific functions of MEG3 in HGSOC, we firstly measured its abundance in a panel of HGSOC cell lines compared to HOSE and FT194, showing that MEG3 downregulation could be a common step in cancer development, independently of cell of origin." (PMID 32295169, 2020). "However, there is a lack of data concerning circulating MEG3 in cancer." (PMID 31231466, 2019). "Finally, we found a correlation between Rb pathway disruption and MEG3 levels in human lung tumors, and taken together, these data suggest that disruption of the pRb-DNMT1 pathway leads to a decrease in MEG3 expression, thereby contributing to the pro-proliferative state of certain cancer cells." (PMID 27832204, 2016). "Results indicated that these treatments had no any effects on serum levels of MEG3, SNHG16 and MALAT1, which provides a base for cancer diagnosis as the useful and stable biomarkers." (PMID 27793008, 2016).
infection (10 papers, 2011 to 2025). The state of being infected such as from the introduction of a foreign agent such as serum, vaccine, antigenic substance or organism. "MEG3 was downregulated in IFN-γ-treated THP1-derived-macrophages after infection with Mbv BCG, but it was upregulated in M. smegmatis (Msm) infected cells." (PMID 37153158, 2023). "As expected, infection of DLD1 cells with the adenovirus-Meg3 interference construct resulted in a decrease in luciferase activity, which was restored by the introduction of a miR-708 antagomir." (PMID 34934045, 2021). "To further confirm the role of Meg3 in mitochondrial fission and podocyte damage, we generated Meg3-overexpressing (OE) podocytes by infection with lentivirus-expressing Meg3." (PMID 32994406, 2020). "Secondly, infection of the two cell lines with MEG3-overexpression lentivirus resulted in increased MEG3 expression levels, whereas SRGAP1 expression was downregulated at the mRNA and protein levels." (PMID 29050236, 2017). "Moreover, the in vitro porcine alveolar macrophage model can only simulate local infection, and the regulatory mechanism of the MEG3/ssc-miR-135/CASP8 axis during systemic infection requires further evaluation in animal models or using different cell lines." (PMID 41156747, 2025). "As already examined in a different context, it can be assumed that MEG3 regulates TGF-β also during macrophage infection with the non-pathogenic MS, which remains to be examined experimentally." (PMID 30818784, 2019). "Arrayed quantification showed infection-dependent repression of several lncRNA including MEG3." (PMID 26757825, 2016). "The maternally expressed ncRNA Meg3/Gtl2 is expressed in the mouse brain, inner ear and eye, displaying differently spliced isoforms in the different tissues, and in response to infection by several encephalitic viruses the 3.2 kb noncoding VINC locus is expressed in the mouse brain." (PMID 21789175, 2011). "MA10 infection induced seven additional down-regulated (Hsp90aa1, Tcf7l2, Gnas, Sparcl1, Ywhag, Cpe, Sparc) and four upregulated DEGs (Ppp1r1b, Penk, Arpp21, Pcp4), whereas Aβ pathology resulted in five down-regulated (Cplx1, Syp, Meg3, Snhg11, Penk) and one upregulated DEG (Psen1)." (PMID 41497643, 2025). "To further confirm the function of the Meg3/miR-708/SOCS3 axis in CRC development, we altered the expression of Meg3 and SOCS3, either alone or together, in the colons of ApcminmiR-708−/− mice or Apcmin mice using adenovirus-mediated infection in vivo." (PMID 34934045, 2021). "There are no reports about involvement of MEG3 in any case of infection." (PMID 26757825, 2016).
neurodegenerative disease (9 papers, 2022 to 2025). A disorder of the central nervous system characterized by gradual and progressive loss of neural tissue and neurologic function. "Not only associated with hyperglycemic conditions, MEG3 levels are also dysregulated in various neurodegenerative diseases." (PMID 40765563, 2025). "In addition to its association with hyperglycemic conditions, dysregulation of MEG3 expression has been implicated in the pathogenesis of various cardio-cerebrovascular and neurodegenerative diseases, largely through its involvement in apoptosis, inflammation, and oxidative stress pathways." (PMID 40765563, 2025). "Recently, dysregulation of MEG3 levels was also observed in various neurodegenerative diseases." (PMID 40765563, 2025). "Several identified lncRNAs play crucial roles in neuron function and maintenance in neurodegenerative diseases, such as Tug1, participating in normal photoreceptor development and contributing to rod differentiation and survival, and Meg3, regulating the process of light-induced retinal damage." (PMID 37811327, 2023). "Studies have shown that lncRNAs such as MEG3 could act as competing endogenous RNA (ceRNA) or form RNA-DNA triplex structures, thereby regulating downstream genes and hence playing an important role in tumorigenesis and degenerative disease." (PMID 35054086, 2022). "Dysregulated lncRNAs upon WS treatment included BACE1-AS, MALAT1, SNHG1, HOTAIR, MEG3, BDNF-AS, and SHANK2-AS1 which are potential biomarkers in several neurodegenerative diseases." (PMID 40928594, 2025). "Given the significantly downregulated PI3K/Akt pathway in R45W-iPRCs observed in this study and the downregulation of Akt in RP retinas, the downregulation of MEG3 suggests potential therapeutic approaches to OMD or even broader photoreceptor and nervous system degenerative diseases." (PMID 40450528, 2025).
cardiovascular diseases (8 papers, 2018 to 2024). "Our findings indicate that Meg3 might be associated with cardiovascular disease development." (PMID 30838022, 2019). "In conclusion, MEG3 is expected to be used in the diagnosis of some cardiovascular diseases, but it still needs to be identified with a large sample size, and the relationship between genes and diseases still needs further experimental studies." (PMID 36968595, 2023). "Currently, studies on lncRNA MEG3 in cardiovascular diseases are relatively rare, and there is still a large space for exploration." (PMID 36523500, 2022). "At the same time, MEG3 has gradually gained attention in cardiovascular disease, a major human public health problem." (PMID 36523500, 2022). "lncRNA MEG3 plays a preventive and/or therapeutic role in cardiovascular diseases by reducing inflammatory injury, apoptosis and endoplasmic reticulum stress." (PMID 36523500, 2022). "Mycobacterial infection, causes autophagy induction and Meg3 downregulation in macrophages, however the relationship between Meg3, autophagy, and cardiovascular diseases needs to be further explored." (PMID 34207151, 2021). "Our findings provide novel insights on the role of Meg3 in endothelial cell injury and suggest Meg3 as a potential target to prevent and repair endothelial cell damage for the prevention and treatment of cardiovascular diseases." (PMID 30838022, 2019). "Endothelial cell dysfunction in vasculature occurs during the human aging process, which can contribute to development of cardiovascular diseases Gtl2/Meg3 was among to highest expressed lncRNAs in endothelial cells from human umbilical vein." (PMID 29996488, 2018). "If we could establish the characteristic relationship between lncR-Meg3 and markers of myocardial injury, it would more strongly prove that MEG3 can be used as a biomarker for the cardiovascular diseases listed." (PMID 36968595, 2023). "Although some knowledge has been gained about the benefits of lncRNA MEG3 for cardiovascular disease from experimental data, it is worth noting that its specific underlying mechanisms are still relatively unknown." (PMID 36523500, 2022). "Taken together, these results suggest that MEG3 may be involved in the etiology of cardiovascular diseases of offspring born in an intrauterine high-estradiol environment." (PMID 35047570, 2021). "Taken together, Gtl2/Meg3 appears to generally suppress neovascularization, and modulating Gtl2/Meg3 activity could have utility in replenishing vasculature for diverse cardiovascular disease contexts." (PMID 29996488, 2018).
metabolic disease (8 papers, 2019 to 2024). A congenital disorder (due to inherited enzyme abnormality) or acquired (due to failure of a metabolically important organ) disorder resulting from an abnormal metabolic process. "Several lncRNAs, including maternally expressed gene 3 (Meg3), have been identified as ceRNAs implicated in pathophysiological processes of metabolic disorders." (PMID 32614631, 2020). "Increasing evidence has implicated Meg3 in metabolic disorders." (PMID 32614631, 2020). "Therefore, the function of Meg3 in the development of metabolic disorders may be tissue specific." (PMID 32614631, 2020).
cardiac disease (4 papers, 2016 to 2023). "The lncRNA databases also recommend other heart disease-related lncRNAs, which were differentially expressed in particular ANT-treated conditions, including MALAT1, MEG3, TUG1, GAS5, CASC1S." (PMID 35415316, 2022).
bacterial infection (3 papers, 2017 to 2023). "Another study found that MEG3 regulates the immune response to bacterial infection in lungs through binding to miR-138 competitively with IL-1β, increasing IL-1β concentration." (PMID 36869839, 2023). "A recent study in mice characterized MEG3 as a novel pulmonary inflammatory regulator of bacterial infection through miR-138." (PMID 28611953, 2017).
hematological malignancies (3 papers, 2018 to 2023). "Overall, MEG3 could serve as a novel therapeutic target for several types of hematological malignancies." (PMID 31480503, 2019). "Moreover, MEG3 is also considered to be inhibited in other cancers, including HCC, NB, glioma, meningioma, bladder cancer, and hematological malignancies." (PMID 31480503, 2019).
kidney diseases (3 papers, 2021 to 2024). "Owing to the complexity of kidney disease, it is tempting to speculate the detailed function of renal disease-associated variants present in this MEG3 gene; however, further research will be necessary to elucidate the role of MEG3 in CKD in the Tiwi population." (PMID 38347632, 2024).